MAML2 (mastermind like transcriptional coactivator 2)
Diseases named in the same sentence as MAML2 in open-access papers (continued):
Sharing a sentence is not in itself a finding about the gene and the disease.
breast carcinoma (8 papers, 2014 to 2024). "MAML2 is abnormally expressed in various cancers, for example, MAML2 enhancer region methylation is significantly increased in breast cancer and squamous cell carcinoma." (PMID 38427106, 2024). "MAML2 enhancer was hypomethylated and its expression was at a high level in breast cancer." (PMID 38427106, 2024). "MAML2 (mastermind‐like transcriptional coactivator 2) is also a transcription coactivator that regulates the Notch signaling pathway and can function as an oncogene in breast cancer." (PMID 36476410, 2022). "Moreover, in a breast cancer cell line, the promoter of MAML2 oncogene is demethylated, leading to the activation of MAML2, which activates the NOTCH oncogene signaling pathway." (PMID 33878138, 2021). "Furthermore, in the same investigation, the authors revealed that PTS was able to downregulate MAML2, to induce alteration in DNA methylation, to decrease gene expression, and prevent the invasive properties of breast cancer cells and their ability to anchorage-independent growth." (PMID 35327559, 2022). "Our findings were further validated using qRT-PCR, western blotting and immunohistochemistry which show decreased expression of NLGN3, MAML2, ANK2, and SYNE1 in breast cancer cell lines as MCF7 and MDA-MB-231 as compared to control cell line MCF10A." (PMID 38977697, 2024). "In contrast, resveratrol (15 μM) treatment for 9 days increased DNMT3B activity that led to the hypermethylation and silencing of the MAML2 (mastermind-like protein 2; co-activator of the oncogenic NOTCH signaling pathway) gene in MCF10CA1h and MCF10CA1a human breast cancer cell lines." (PMID 32878338, 2020).
glioblastoma (8 papers, 2016 to 2024). The most malignant astrocytic tumor (WHO grade IV). "In glioblastoma multiforme, LINC01152 can upregulate the expression of MAML2 via the Notch signaling pathway to promote glioblastoma multiforme tumorigenesis." (PMID 34777473, 2021).
ovarian carcinoma (8 papers, 2018 to 2024). A malignant neoplasm originating from the surface ovarian epithelium. "To assess the effect of YM depletion on tumor growth in vivo, we generated ovarian cancer ES-2 cells that express luciferase (ES-2-luc) and subsequently transduced them with pLKO.1 lentiviruses carrying either shCtl or shM2-3 targeting YM/MAML2." (PMID 39624057, 2024). "The YM fusion in ovarian cancer ES-2 cells comprises two functional domains: YAP1 (1–328 aa) and MAML2 (172–1153 aa)." (PMID 39624057, 2024). "We further confirmed that MAML2 knockdown in a YM-fusion-negative ovarian cancer cell line, Heya-8, did not significantly affect cell growth or apoptosis, further supporting an essential role of the YM fusion in the sustained growth of YM-positive cancer cells." (PMID 39624057, 2024).
adenoid cystic carcinoma (7 papers, 2019 to 2026). A malignant tumor arising from the epithelial cells. "In the last decade, advances in molecular techniques have demonstrated recurrent genetic alterations in some salivary gland tumors, including the fusion of genes such as ETV6 in secretory carcinoma, MYB and MYBL1 in adenoid cystic carcinoma, and MAML2 in MEC." (PMID 39958930, 2025).
salivary gland mucoepidermoid carcinoma (7 papers, 2013 to 2025). A carcinoma that arises from the salivary glands. "Sclerosing mucoepidermoid carcinoma of the salivary gland with eosinophilia is a rare tumor mostly negative for the MAML2 rearrangement commonly seen in salivary mucoepidermoid carcinoma." (PMID 37305870, 2023).
glioma (6 papers, 2019 to 2025). A benign or malignant brain and spinal cord tumor that arises from glial cells (astrocytes, oligodendrocytes, ependymal cells). "We found that TFs encoded by HOX genes recurrently appeared in glioma, and these TFs regulated critical genes (such as MAML2, CDK6, FAM84B, and PTBP1)." (PMID 33537074, 2021). "Among the seven MAML2 SNPs, two SNPs (rs7938889 and rs485842) were found to be significantly related to the risk of glioma by an adjustment for age and gender." (PMID 31652449, 2019). "We found that MAML2 rs7938889 and rs485842 polymorphisms were significantly associated with the reduced risk of glioma." (PMID 31652449, 2019). "Kaplan–Meier survival analysis and univariate, multivariate Cox proportional hazard regression analyses for hazard ratios (HRs) and 95% CIs were performed to evaluate the contribution of MAML2 polymorphisms to glioma prognosis." (PMID 31652449, 2019). "In the present study, four SNPs in MAML2 (rs7938889 and rs485842, rs7115578 and rs4598633) were found to be significantly associated with glioma risk." (PMID 31652449, 2019). "In the present study, we first investigated the association between MAML2 genetic variants and glioma risk or prognosis among the Chinese Han population." (PMID 31652449, 2019). "We investigated the association between MAML2 polymorphisms and the prognosis of glioma patients using Log-rank tests and univariate Cox regression analysis." (PMID 31652449, 2019). "Strengths of the current study include the relatively large sample size considering the rarity of glioma, and the first demonstration on the associations of MAML2 polymorphisms with glioma risk and prognosis among Chinese Han population." (PMID 31652449, 2019). "In this hospital-based case–control study, we aimed to investigate the association of MAML2 polymorphisms with the susceptibility of glioma, and the role of these polymorphisms in the prognosis of glioma patients among the Chinese Han population." (PMID 31652449, 2019). "Second, the detailed molecular mechanism under which MAML2 polymorphisms affect glioma risk and prognosis needs further studies to elucidate." (PMID 31652449, 2019). "Logistic regression was used to estimate the association between MAML2 polymorphisms and glioma risk by calculating odds ratios (ORs) and 95% confidence intervals (CI)." (PMID 31652449, 2019). "We aimed to investigate the role of MAML2 polymorphisms in glioma risk and prognosis among the Chinese Han population." (PMID 31652449, 2019). "Meanwhile, Notch1 pathway‐related genes, including Maml2, Ccn3, Fat4, Cdh6, and Ptp4a3, exhibited similar expression trends and may be intimately linked to glioma development." (PMID 39544152, 2024). "A study based on glioma microarray data identified MAML2 as a novel gene associated with glioma." (PMID 38427106, 2024). "Moreover, low expression of MAML2 was associated with a poor OS for glioma, especially lower grade glioma." (PMID 31652449, 2019). "In conclusion, these results suggested that MAML2 polymorphisms might contribute to glioma susceptibility and prognosis." (PMID 31652449, 2019). "Our study addressed a gap in knowledge of the MAML2 gene polymorphisms and the susceptibility and prognosis of glioma, indicating that MAML2 genetic variations might play an important role in the development of glioma." (PMID 31652449, 2019). "MAML2 rs7115578 polymorphism was only one that affected the prognosis of glioma in the overall." (PMID 31652449, 2019). "However, the relevance of MAML2 variants with glioma remains unknown." (PMID 31652449, 2019). "Third, variants in CCDC26 (the 8q24 locus), C2orf80 (close to IDH), LRIG1, PHLDB1, ETFA, MAML2 and ZBTB16 were associated with IDH-mutant glioma." (PMID 31842352, 2019). "Based on microarray data of glioma, MAML2 as a novel gene related to glioma was identified." (PMID 31652449, 2019). "Risk variants in LRIG1, PHLDB1, ETFA, MAML2 and ZBTB16 were also associated with IDH-mutant glioma." (PMID 31842352, 2019).
glioma (continued). "Furthermore, we extracted MAML2 expression data between glioma patients and healthy controls from GEPIA database." (PMID 31652449, 2019). "Furthermore, we observed a significant association between the genetic variants in LRIG1, PHLDB1, ETFA, ZBTB16 and MAML2 and the risk of IDH-mutant glioma." (PMID 31842352, 2019). "Although MAML2 polymorphisms were found to be significantly associated with the risk and prognosis of glioma, the mechanism of MAML2 underlying the effect on the glioma risk and patients survival was not identified in the present study, nor has not been reported in the literature." (PMID 31652449, 2019). "Additionally, MAML2 as a novel gene was abnormal expressed in glioma." (PMID 31652449, 2019). "However, no previous study has investigated the contribution of MAML2 variants to glioma risk and prognosis." (PMID 31652449, 2019). "Compared with normal tissues, we found that MAML2, FAM84B, and CDK6 exhibited higher expression in glioma." (PMID 33537074, 2021). "Moreover, the knockdown target genes (MAML2, FAM84B, and CDK6) significantly inhibited the cell proliferation in glioma (p < 0.001)." (PMID 33537074, 2021). "By bioinformatics analysis, we found that MAML2 gene expression is up-regulated in glioma compared with normal tissue." (PMID 31652449, 2019). "MAML2 and ETFA are currently not established to have a clear role in somatic alterations in glioma." (PMID 31842352, 2019).
ependymoma (5 papers, 2020 to 2024). A WHO grade II, slow growing tumor of children and young adults, usually located intraventricularly. "MAML2 has previously been reported as a gene partner for fusions in supratentorial ependymomas, ZFTA and YAP1 fusion-positive." (PMID 38581034, 2024). "The first is C11orf95-MAML2, a driver fusion formed by a novel exon which joins a truncated exon 5 of C11orf95 with 36 bp of intron 1 of MAML2 in a supratentorial ependymoma." (PMID 32466770, 2020).
hemangioendothelioma (5 papers, 2021 to 2025). A vascular proliferation characterized by the presence of prominent endothelial cells and the formation of vascular channels. "The molecular defects seen in some cases of RH include rearrangements and fusions of YAP1 and MAML2 genes, also seen in cases of composite hemangioendotheliomas." (PMID 33593408, 2021). "Notably, this variant shows more aggressive clinical behavior than conventional composite hemangioendothelioma and is associated with fusions of the PTBP1::MAML2 or EPC1::PCH2 genes; single cases also harbored YAP1::FOXR1 and ARID1B::MAML2 fusions." (PMID 39264472, 2024). "Additionally, a frequent fusion of YAP1 with the MAML2 gene has been reported both in conventional composite hemangioendothelioma and in hobnail (retiform) hemangioendothelioma, highlighting the close relationship of these two entities." (PMID 39264472, 2024).
lymph node metastasis (5 papers, 2015 to 2025). "Our research showed that the TNM stage, histological grade, lymph node metastasis, and MAML2 gene translocation all had a significant effect on the prognosis of PMEC patients." (PMID 35747926, 2022). "The univariate analysis of the survival of patients with PMEC showed that TNM stage, histological grade, lymph node metastasis, and MAML2 gene translocation had significant influences on survival in patients with PMEC." (PMID 35747926, 2022). "Gender, lymph node metastasis, MAML2 rearrangement, and chemotherapy (CHT) and/or radiotherapy (RT) had no prognostic significance." (PMID 26575266, 2015). "In contrast, MAML2-negative MECs are more likely to be HG, with a higher rate of lymph node metastases and local recurrences." (PMID 40362000, 2025). "Patients with advanced disease, those with a negative MAML2 gene translocation, with lymph node metastases, and high‐grade malignancies have a poor prognosis." (PMID 35747926, 2022).
salivary gland tumors (5 papers, 2020 to 2025). "Thus, MAML2 rearrangements were found primarily in salivary gland tumors with a small subset of MAML2+ tumors with unusual histology and uncommon fusion partners outside the head and neck region." (PMID 35457138, 2022). "Only five MAML2 rearranged tumors were found outside the head and neck region (0.06%) and a review of the medical record showed no prior or subsequent diagnosis of a salivary gland neoplasm in these patients." (PMID 35457138, 2022).
NUT carcinoma (4 papers, 2015 to 2024). "All these entities are either defined or can be verified by molecular markers such as PLAG1 fusions in myoepithelial carcinoma, EWSR1::FLI1/ERG fusions in adamantinoma-like Ewing sarcoma, NUTM1 fusions in NUT carcinoma, MAML2 fusions in MEC, YAP1::MAML2 fusion in squamoid porocarcinoma, and others." (PMID 38630141, 2024).
brain tumors (3 papers, 2019 to 2024). "In vivo, mutation of the TEAD binding site of YAP in YAP::MAML2, YAP::MAMLD1, YAP::FAM118B, YAP::SS18, and YAP::TFE3 significantly reduced the oncogenic potential of these protein fusions to initiate brain tumors in mice." (PMID 40491864, 2024). "Working in vivo, multiple studies demonstrated that several YAP fusion proteins, such as YAP::FAM118B, YAP::MAML2, YAP::MAMLD1, YAP::SS18, and YAP::TFE3, can induce brain tumors and/or muscle tumors in mice." (PMID 40491864, 2024).
melanoma (3 papers, 2016 to 2023). A malignant, usually aggressive tumor composed of atypical, neoplastic melanocytes. "Diacylglycerol kinase (DGKB), TGc domain-containing protein (Tgm2), structural maintenance of chromosomes 4 (SMC4) and mastermind-like transcriptional coactivator 2 (MAML2) were related to lipid metabolism, facilitating melanoma development in the severe-EMN group." (PMID 35202347, 2022).
acute myeloid leukemia (2 papers, 2017 to 2020). Acute myeloid leukemia (AML) is a group of neoplasms arising from precursor cells committed to the myeloid cell-line differentiation. "One of its rare partner genes, mastermind like 2 (MAML2) gene has been reported in four cases of myeloid neoplasms after chemotherapies: two cases of acute myeloid leukemia (AML) and two cases of myelodysplasic syndromes (MDS)." (PMID 28535805, 2017). "One of its rare fusion partners, the mastermind like 2 (MAML2) gene has been reported in four cases of myeloid neoplasms after chemotherapy so far: two acute myeloid leukemias (AML) and two myelodysplasic syndrome (MDS), and two cases of secondary T-cell acute lymphoblastic leukemia (T-ALL)." (PMID 28535805, 2017).
lymphoma (2 papers, 2020 to 2023). A malignant (clonal) proliferation of B- lymphocytes or T- lymphocytes which involves the lymph nodes, bone marrow and/or extranodal sites. "Interestingly, high levels of expression of MAML2 are detectable in B cell-derived lymphoma types, when compared to normal tonsillar B cells." (PMID 33425921, 2020).
neuroblastoma (2 papers, 2019 to 2020). Neuroblastoma (NB) is the most common solid, extracranial childhood tumor. "We conclude that MES-specific SEs are associated with NOTCH2 and MAML2 and that mesenchymal neuroblastoma cells have transcriptional activation and signaling of the NOTCH pathway." (PMID 30948783, 2019). "ChIP-sequencing analysis of H3K27ac revealed SEs8,9 within the gene bodies of NOTCH2 and MAML2 that were specific for MES-type neuroblastoma cells." (PMID 30948783, 2019). "Notch pathway targets and effectors were highly induced in our RNA-seq of IMR32 treated with BMP4, so we first validated a panel of Notch pathway genes, including HES1, MAFB, MAML2 and NOTCH3, confirming a BMP4-Notch signaling pathway in neuroblastoma." (PMID 32210188, 2020). "The same super-enhancers of NOTCH2 and MAML2 were observed in neural crest cells, corroborating the idea that MES-type neuroblastoma cells are neural crest-like." (PMID 30948783, 2019).
odontogenic cyst (2 papers, 2021 to 2023). A cyst in the jaw that arises from tissues of tooth development. "Our review of the literature identified 36 cases of MAML2-rearranged intraosseous lesions of the jaw (30 central MECs, 5 odontogenic cysts with mucous prosoplasia, and 1 glandular odontogenic cyst)." (PMID 37082423, 2023). "An aggressive behavior of glandular odontogenic cyst has been described and microscopic differential diagnosis from central mucoepidermoid carcinoma is still debaTable to date, even with MAML2 rearrangement." (PMID 34824702, 2021).
pancreatic cancer (2 papers, 2016 to 2022). "Notch signaling components Jag1, Maml2, and Maml3 are direct targets of miR-200 inhibition in breast and pancreatic cancer cell lines." (PMID 36076302, 2022). "The ability of pancreatic cancer cells to form tumor spheres was reduced through inhibition of the Notch pathway (achieved using γ-secretase inhibitors or knockdown of Jag1/Maml2/Maml3) suggesting that cell stemness of CSCs can be induced through the Notch pathway." (PMID 36076302, 2022).
sarcoma (2 papers, 2017 to 2022). A usually aggressive malignant neoplasm of the soft tissue or bone. "Here we report the case of a KMT2A - MAML2 fusion discovered by Next-Generation Sequencing (NGS) analysis in front of an inv11 (q21q23) present in a 47-year-old female previously treated for a sarcoma in 2014, who had a B acute lymphoid leukemia (B ALL)." (PMID 28535805, 2017).
thymic epithelial tumors (2 papers, 2014 to 2026). "It is necessary for the further study to clarify if MAML2 rearrangement presents in the rare MEC component of combined thymic epithelial tumors." (PMID 24444077, 2014). "The MAML2 gene fusions (KMT2A::MAML2, YAP1::MAML2, and CRTC1::MAML2), which have been observed in a small subset of thymic epithelial tumours, were not identified in our cohort." (PMID 41344988, 2026).
acinic cell carcinoma (1 paper, 2025). "However, carcinomas may frequently display a diffuse oncocytic phenotype, being classified by their characteristic features (e.g., AR-positive salivary duct carcinoma, MEC with MAML2 rearrangements, secretory carcinoma with ETV6 NTRK3 gene fusion, and DOG1- and SOX10-positive acinic cell carcinoma)." (PMID 41440486, 2025).
adenosquamous carcinoma (1 paper, 2014). A carcinoma composed of malignant glandular cells and malignant squamous cells. "Our study also revealed negative rearrangement for MAML2 in the total 40 cases of adenosquamous carcinomas." (PMID 24714697, 2014). "We detected MAML2 rearrangement using fluorescence in situ hybridization (FISH) in tissue samples from 42 cases of PMEC and 40 of adenosquamous carcinoma (ASC), and the expression of potential downstream targets of MECT1-MAML2, including HES1, FLT1 and NR4A2 with immunohistochemistry (IHC)." (PMID 24714697, 2014).
astroblastoma (1 paper, 2021). "Our data are in line with this report as our three cases with ZFTA:MAML2 were classified as cluster 2 and showed a histological phenotype of EPN but also of astroblastoma." (PMID 34389065, 2021).
Bovine mastitis (1 paper, 2023). INFLAMMATION of the UDDER in cows. "For many of the genes that overlapped with dMHB discriminant signatures in this study, such as ZNF691, MAML2, ZC2H7B, CD101, TSPAN32, and MAML2, this is the first report of their involvement in bovine mastitis." (PMID 37373515, 2023).
breast tumors (1 paper, 2020). "Our findings suggest that the assessment of rearrangements involving PLAG1 or HMGA2 in breast PAs, and of MAML2 rearrangements in breast MECs, might be used as ancillary tools to aid in the diagnosis of these rare breast tumors." (PMID 32550265, 2020).
Cluster headache (1 paper, 2021). A type of headache characterized by repeated attacks of unilateral pain lasting 15 to 180 minutes and associated with local autonomic signs. "One of the Notch signaling genes, MAML2, was differentially expressed in cluster headache patients." (PMID 33859262, 2021).
diffuse astrocytoma (1 paper, 2025). A low-grade (WHO grade II) astrocytic neoplasm. "“MYB- or MYBL1-altered diffuse astrocytoma” is a rare entity defined by a canonical fusion event of MYB- or MYB1L, with the most common partner genes PCDHGA1, MMP16, and MAML2." (PMID 40392954, 2025).
graft versus host disease (1 paper, 2021). An immune system disorder that occurs after allogeneic hematopoietic stem cell transplant and is a reaction of donor immune cells against host tissues. "In contrast, SW620 DEGs were characterized by an enrichment in IFN and TNF signaling, ROS and NOTCH pathways (Jagged1, MAML2), but not in graft-versus-host disease or allograft rejection pathways." (PMID 33608544, 2021).